U3 (Small nucleolar RNA U3 )
Synonyms: LOC124906381
Gene: Small nucleolar RNA gene on chromosome 3 (90,030,284 to 90,030,495, forward strand). Ensembl gene ENSG00000212598.
Gene Ontology:
Biological process: RNA processing
Cellular component: nucleolus
Homologues: Orthologues: macaque U3 (92% identical). Paralogues in human: SNORD3E (76% identical), U3 (75% identical), SNORD3P1 (75% identical), U3 (74% identical), U3 (73% identical), SNORD3G (73% identical), U3 (72% identical), SNORD3H (72% identical), U3 (71% identical), SNORD3D (71% identical), U3 (70% identical), U3 (69% identical), and 12 more.